NYNRIN (NYN domain and retroviral integrase containing)
Synonyms: CGIN1; KIAA1305; FLJ11811
Tractability: Antibody: UniProt predicts a signal peptide or a membrane-spanning region.
Gene: Protein-coding gene on chromosome 14 (24,399,003 to 24,419,304, forward strand). Ensembl gene ENSG00000205978.
Subcellular location: Membrane
Subcellular location (Human Protein Atlas): Golgi apparatus; Nucleoplasm; Vesicles
Gene Ontology:
Molecular function: mRNA binding; RNA endonuclease activity; DNA-directed DNA polymerase activity; nucleic acid binding; RNA-DNA hybrid ribonuclease activity
Biological process: 3'-UTR-mediated mRNA destabilization; DNA biosynthetic process; DNA integration; DNA-templated DNA replication
Cellular component: cytoplasmic ribonucleoprotein granule; nucleus; chromosome; membrane
Genetic constraint (gnomAD): Loss-of-function variants: 86 observed, 147.88 expected, observed/expected ratio (o/e) 0.58, 90% interval 0.49 to 0.7. The upper end of that interval is the gene's LOEUF score, 0.7, which puts it in group 2 of 6, group 1 being the genes least tolerant of losing a copy. Missense variants: 2,184 observed, 2,445.7 expected, observed/expected ratio (o/e) 0.89, 90% interval 0.86 to 0.93. Synonymous variants: 1,023 observed, 1,037.7 expected, observed/expected ratio (o/e) 0.99, 90% interval 0.94 to 1.04.
Homologues: Orthologues: chimpanzee NYNRIN (99% identical), macaque NYNRIN (97% identical), dog NYNRIN (86% identical), pig NYNRIN (85% identical), guinea pig NYNRIN (85% identical), rabbit NYNRIN (83% identical), rat Nynrin (77% identical), mouse Nynrin (76% identical), zebrafish khnyn (12% identical), tropical clawed frog khnyn (12% identical), Caenorhabditis elegans rege-1 (6% identical), Drosophila melanogaster Regnase-1 (6% identical), and 4 more. Paralogues in human: KHNYN (15% identical), N4BP1 (11% identical), ZC3H12C (9% identical), ZC3H12B (7% identical), ZC3H12A (7% identical), ZC3H12D (6% identical).
Diseases named in the same sentence as NYNRIN in open-access papers:
NYNRIN is named in the same sentence as 10 diseases in open-access papers, as found by Europe PMC text mining. Sharing a sentence is not in itself a finding about the gene and the disease. The quoted sentences say what the papers report.
Wilms tumor (6 papers, 2019 to 2024). An embryonal neoplasm characterized by the presence of epithelial, mesenchymal, and blastema components. "Analyzing exome sequencing of lymphocyte DNA from Wilms tumor involving 890 individuals has shown that TRIM28, FBXW7, KDM3B, and NYNRIN are new predisposition genes of Wilms tumor." (PMID 38926399, 2024). "BOLA-DQB encoded a major histocompatibility complex, whose expression was altered in malignant cancers in humans; NYNRIN was shown to be a predisposing gene for Wilms tumor that causes common renal cancer in children." (PMID 32575783, 2020). "In detail, NYNRIN gene was related to Wilms tumor predisposition." (PMID 38322112, 2024). "The four new Wilms tumour predisposition genes identified—TRIM28, FBXW7, NYNRIN, and KDM3B—are involved in diverse biological processes and, together with the other 17 known Wilms tumour predisposition genes, account for about 10% of Wilms tumour cases." (PMID 30885698, 2019). "Biallelic truncating mutations in NYNRIN were identified in three individuals with Wilms tumour, which is highly unlikely to have occurred by chance (p<0·0001)." (PMID 30885698, 2019).
hypogonadism (1 paper, 2025). A disorder characterized by decreased function of the gonads. "NYNRIN, a liver enzyme gene, was uniquely identified in colocalization analysis of hypogonadism and gene expression." (PMID 40316537, 2025). "NYNRIN, TUFM, and SH2B1 were uniquely identified by colocalization analysis of hypogonadism, while NF1, PABPC4, and SHROOM3 were uniquely identified through colocalization analysis of total testosterone." (PMID 40316537, 2025).
Intellectual disability (1 paper, 2019). "There are indications that KDM3B and NYNRIN mutations might cause non-malignant phenotypes, particularly intellectual disability." (PMID 30885698, 2019).
periodontitis (1 paper, 2025). An acute or chronic inflammatory process that affects the tissues that surround and support the teeth. "These genes have been previously implicated in oxidative stress (GPX2 and GSTA4), immune regulation (CD34 and IGKV2D-30), and RNA processing (NYNRIN), which are all biologically relevant to the inflammatory and immune mechanisms underlying periodontitis." (PMID 41333919, 2025). "Lastly, we found an upregulation trend of NYNRIN in the gingival tissue of periodontitis patients." (PMID 41333919, 2025). "The corresponding results revealed that, compared to control samples, IGKV2D-30 and CD34 were downregulated in patients with periodontitis, while GPX2, GSTA4, and NYNRIN were upregulated in patients with periodontitis." (PMID 41333919, 2025). "Similarly, GSTA4 (5 SNPs, OR = –0.205, 95% CI: –0.391 to –0.020, p=0.031), NYNRIN (5 SNPs, OR = –0.174, 95% CI: –0.298 to –0.050, p=0.006), and IGKV2D-30 (3 SNPs, OR = –0.405, 95% CI: –0.809 to –0.002, p=0.049) were all inversely associated with periodontitis, implying potential protective roles." (PMID 41333919, 2025).
systemic lupus erythematosus (1 paper, 2025). An autoimmune multi-organ disease typically associated with vasculopathy and autoantibody production. "Conversely, the low expression of NYNRIN was enriched in pathways, including systemic lupus erythematosus, N-glycan biosynthesis, among others." (PMID 41333919, 2025).
tumor (3 papers, 2016 to 2024). "At the time of diagnosis, the tumor cells had four distinct SNVs in USP54, GABRA3, KRAS and SETD2, while the relapsed tumor acquired four additional unique mutations in MYH7, NYNRIN, ODZ1 and ZIC3." (PMID 26527318, 2016). "The results showed that IL2RA, DNMT3B, ADRM1, and NRIP1 were highly expressed in tumor tissue compared to normal tissue, while ALDH2, NYNRIN, LSP1, and CALCRL were the opposite." (PMID 38322112, 2024).
cancer (1 paper, 2019). A tumor composed of atypical neoplastic, often pleomorphic cells that invade other tissues. "We did not identify biallelic NYNRIN protein-truncating variants in individuals with other childhood or adult cancers." (PMID 30885698, 2019).
NYNRIN also shares sentences with these, for which no sentence is quoted: Hypercholesterolemia (1 paper); leukemia (1); renal carcinoma (1).